ENSG00000205236 (novel protein, UPK3BL-RASA4 readthrough)
Gene: Protein-coding gene on chromosome 7 (102,582,523 to 102,642,869, reverse strand). Ensembl gene ENSG00000205236.
Genetic constraint (gnomAD): Missense variants: 0 observed, 17.83 expected, observed/expected ratio (o/e) 0, 90% interval 0 to 0.17. Synonymous variants: 1 observed, 6.18 expected, observed/expected ratio (o/e) 0.16, 90% interval 0.057 to 0.77.